S100A4 (S100 calcium binding protein A4)
Diseases named in the same sentence as S100A4 in open-access papers (continued):
Sharing a sentence is not in itself a finding about the gene and the disease.
pancreatic cancer (continued). "However, information on S100A4 expression in thyroid tumour cells is limited thus far, although high S100A4 expression in breast, ovary, colon, gastric, and pancreatic carcinomas has been reported." (PMID 16265347, 2005). "Indeed, S100A4 is highly expressed in many types of cancer such as breast cancer and particularly gastrointestinal cancers, including colorectal, gastric, esophageal, and pancreatic cancer." (PMID 26903691, 2016). "Moreover, in previous studies we have proposed the hypothesis that S100A4 gene might be one of the key factors in EMT molecular network regulated by Shh-Gli1 signaling pathway in pancreatic cancer cells." (PMID 25072505, 2014). "Some studies have implied that S100A4 could be used as a potential biomarker of pancreatic cancer." (PMID 25072505, 2014). "Thus, it seems that S100A4 mediated by abnomal activated Shh-Gli1 signaling pathway could be one of key pro-migration factors in pancreatic cancer cells." (PMID 25072505, 2014). "Furthermore, S100A4 has been shown to have prognostic value in a number of human cancers such as breast, oesophageal-squamous, non-small cell lung, primary gastric, malignant melanomas, prostate and pancreatic carcinomas, besides bladder cancer." (PMID 21979422, 2011). "In our study, the transcripts of both S100A4 and S100A6 were found at a high level in the HPNE cells when compared to the pancreatic cancer cells." (PMID 37627239, 2023). "In pancreatic cancer, GLI1 regulates EMT through specific target genes such as TGF-β, Ras, Wnt, P13K/AKT, and S100A4." (PMID 37139482, 2023). "Interestingly, the combined decrease in S100A4 and fibronectin levels we specifically observed in the spleen of curcumin-treated rats found an echo in the findings of one previous study reporting a connection between Hedgehog signaling and S100a4 regulation in pancreatic cancer cells." (PMID 35873564, 2022). "In vitro, the activation of NF-κB upon the interaction of S100A4 with RAGE has been reported in various cancer cells, including human osteosarcoma (II-11b), human melanoma (A375, B16-F10), and human pancreatic cancer (BxPC-3) cells." (PMID 36613714, 2022). "An increase in S100A4 protein expression has been correlated with a worse prognosis for patients with different types of cancer including breast, colon, gastric, lung, hepatocellular, and pancreatic cancer, which suggested that OSX could be used as a target gene to improve cancer prognosis." (PMID 30450809, 2019). "S100A4 can activate the Src and focal adhesion kinase (FAK) signaling and promote tumorigenic behaviors of pancreatic cancer cells." (PMID 29069865, 2017). "S100A4 promotes activation of Src and FAK, which form a dual signaling pathway and contribute to the tumorigenic capacity of pancreatic cancer cells." (PMID 25677816, 2015). "S100A4 can suppress the BNIP3 expression and contributes to chemoresistance and survival in pancreatic cancer cells." (PMID 25677816, 2015). "MMP-7 is assumed to be an important factor in the growth of pancreatic cancer, and the increased expression of MMP-7 in S100a4-Cre; Ext1f/f mice may have led to increased tumor growth." (PMID 36809261, 2023). "For instance, previous studies reported that S100A2 and S100A10 were the negative biomarker for pancreatic cancer (PC), while S100A4 was profoundly involved in the chemoresistance and survival in are negative prognostic biomarkers in PC cells." (PMID 37420211, 2023). "S100A4 may be a useful biomarker for predicting EMT state, disease progression, and outcome in patients with pancreatic cancer." (PMID 36828915, 2023). "In pancreatic cancer studies, it was found that the Shh signaling pathway promotes the process of EMT by affecting the components of various signaling pathways, including TGFβ, Ras, Wnt, PI3K/AKT, Integrin, and S100A4." (PMID 36278239, 2022).
pancreatic cancer (continued). "S100 calcium-binding protein A4, a protein related to cancer metastasis, can promote mitochondrial activity and ATP production via upregulating NDUFS2 expression, which is beneficial to the proliferation and invasion of pancreatic cancer SUIT-2 cells." (PMID 33923185, 2021). "Besides that, sonic hedgehog (SHH)/GLI1 expression induced a significant upregulation of expression level of S100A4, a member of the S100 gene family and a key EMT molecular marker in pancreatic cancer, while E-cadherin was markedly reduced." (PMID 31547193, 2019). "It has been argued that in the pancreatic cancer, Fsp1/S100A4 but not αSMA is the most consistent and predominant mesenchymal marker associated with the EMT program." (PMID 30120146, 2018). "S100A4 overexpression contributed to pancreatic cancer cell perineural invasion and poor clinical outcomes because of the inability of TGF-β1-mediated cell growth inhibition and apoptosis of pancreatic cancer cells." (PMID 29069865, 2017). "Biochemical assays revealed that S100A4 activates Src and focal adhesion kinase (FAK) signaling events, and inhibition of both kinases is required to maximally block the tumorigenic potential of pancreatic cancer cells." (PMID 25677816, 2015). "However, little is known about the interaction among S100A4, Src, and FAK in pancreatic cancer cells." (PMID 25677816, 2015). "S100A4 downregulation results in significant cell growth inhibition and apoptosis in response to TGF-β1, supporting a non-canonical role of S100A4 in pancreatic cancer." (PMID 25677816, 2015). "These include R-RAS and MASP in GC, MAGE1 in melanoma, S100A4 in colon cancer, PAX2 in endometrial cancer, DNMT3A in testicular germ cell tumours, and various genes in pancreatic cancer." (PMID 19107131, 2009). "S100A4 contributes to the suppression of BNIP3 expression, chemoresistance, and inhibition of apoptosis in pancreatic cancer), Whether the expression change of this family member has a certain correlation with the proliferation and apoptosis of hepatoma cells is not clear." (PMID 37420211, 2023). "Our data support that S100A4 has a non-canonical function in pancreatic cancer progression." (PMID 25677816, 2015). "However, our results argue that although S100A4 stimulates both Src and FAK signaling, activation of FAK and Src are not totally dependent upon each other in pancreatic cancer cells." (PMID 25677816, 2015).
colon carcinoma (47 papers, 2002 to 2026). "Increased gene expression levels of S100-A4 are known to promote metastasis and have been linked with chemoresistance in pancreatic and colon cancer cell lines." (PMID 21637840, 2011). "S100A4 overexpression decreases the sensitivity of HT29 colon cancer human cells to MTX, whereas its knockdown causes chemosensitization toward MTX." (PMID 20515499, 2010). "Other reports have indicated that S100 protein can increase Wnt signaling; for example, the role of S100A8 is partially dependent on the activation of Wnt/β-catenin signaling, and inhibition of S100A4 expression impedes colon cancer progression caused by the Wnt/β-catenin signaling pathway." (PMID 35279748, 2022). "Recently, RT-qPCR and dPCR of MACC1 and S100A4 (metastasis-associated in colon cancer 1 and S100 calcium-binding protein A4, respectively) transcripts in serum have been correlated with diagnosis, progression-free survival and overall survival of ovarian cancer." (PMID 34067294, 2021). "Moreover, the metastasis-associated protein S100A4, which has been previously identified in colon cancer cells as an NFAT5 target gene, is very strongly upregulated in CaKi-1 cells." (PMID 25152734, 2014). "For example, S100A4 expression is regulated via the Wnt/β-catenin pathway in human nasal epithelial cells and in colon cancer cells." (PMID 41590823, 2026). "E12 impact on S100A4 mRNA, protein and metastatic phenotype inhibition was effective in both colon cancer cell lines HCT116 and SW620." (PMID 40765817, 2025). "Mice in the Vtnfl/fl S100a4‐Cre+ group demonstrated a notable reduction in both the number and size of colon tumors compared to the Vtnfl/fl S100a4‐Cre‐ group." (PMID 40538300, 2025). "Consistently, GEO dataset analysis revealed that S100A4 expression was significantly increased in UC, CD, and colon cancer tissues compared with that in normal tissues." (PMID 39664586, 2024). "The prognostic significance of S100A4 mRNA levels for disease-free survival with colon cancer revealed by univariate and multivariate COX analysis." (PMID 36895491, 2023). "Other immune cells, such as CD11c- DC and CD8-cytotoxic T cells, tended to decrease in the colon tumors of S100a4-Cre; Ext1f/f mice." (PMID 36809261, 2023). "In colon tumors of the S100a4-Cre; Ext1f/f mice, the number of F4/80-macrophages was significantly lower than that in the control mice." (PMID 36809261, 2023). "S100P promotes EMT, migration and invasion of colon cancer cells by up-regulating S100A4 through AKT activation." (PMID 33842379, 2021). "Hypomethylation of the S100A4 gene, accompanied by an increased protein level, was demonstrated in colon cancer." (PMID 33466593, 2021). "Niclosamide, an approved antihelminthic drug for the treatment of tapeworm infections, inhibited metastasis formation in a mouse model of colon cancer by blocking S100A4 expression and its effects on the WNT/CTNNB1 signaling pathway." (PMID 34078355, 2021). "The expression of S100A4, for example, is mediated by Wnt/β-catenin signalling, a pathway which is highly involved in many cancer types, especially colon cancer." (PMID 32722137, 2020). "Treatment of mice with these inhibitors resulted in decreased tumour growth, reduced invasion, and fewer metastases of colon cancer at least partially due to lower levels of S100A4." (PMID 32722137, 2020). "In vitro treatment with niclosamide inhibited S100a4-induced migration and proliferation of human colon cancer cells." (PMID 29910813, 2018). "Previous studies reported that calcimycin and niclosamide, as transcriptional inhibitors of S100a4, can block S100a4 expression in colon cancer cells, thereby affecting metastasis." (PMID 29910813, 2018).
colon carcinoma (continued). "By conducting this study, we aim to examine the role of S100A4 in the prognosis of colon cancer and to demonstrate its prognostic significance." (PMID 30111999, 2018). "Nevertheless, S100A4‐positive stage II colon cancer patients randomized to adjuvant 5‐fluorouracil and levamisole had a poor outcome with an estimated 3‐year relapse‐free survival of 71% compared to 88% for S100A4‐negative patients." (PMID 27273130, 2016). "Niclosamide affects multiple signaling pathways that are important in cancer progression and has also been shown to block S100A4 expression in colon cancer cells." (PMID 27127879, 2016). "In colon cancer cells NFAT5-mediated upregulation of S100A4 has been shown to be stimulated by Integrins and Src kinase." (PMID 25152734, 2014). "This study investigated 33 colon cancer patients who underwent colonic surgery and evaluated S100A4 expression by RT-PCR, demonstrating that colon patients with high S100A4 expression had a significantly worse OS." (PMID 24188373, 2013). "In vivo data of reduced S100A4 expression in colon cancer of other studies were mainly obtained by inhibiting the hyperactivated Wnt/β-catenin pathway and therefore indirectly reducing the S100A4 transcription." (PMID 22878175, 2012). "It is worth mentioning that a moderate S100A4 overexpression has been described in a colon cancer cell line resistant to doxorubicin." (PMID 20515499, 2010). "In conclusion, we have found that IFN-γ downregulates S100A4 expression in osteosarcoma, breast and colon carcinoma cell lines." (PMID 12799648, 2003). "The present experiments show, for the first time, using markers for T and B lymphocytes, that S100A4 is found exclusively in T lymphocytes, not only in the immune cells of the appendix, but also in specimens of colon carcinoma." (PMID 11875708, 2002). "Similar to this antiviral effect, our results suggest that a decrease in CD80/CD86 expression may be associated with CD8+ T cell reduction in the tumor microenvironment of colon tumor growth of S100a4-Cre; Ext1f/f mice." (PMID 36809261, 2023). "Thus, to examine αSMA differentiation of fibroblasts in the TME, we performed immunostaining for αSMA antibody in MC38 S.C. colon tumor tissues of the S100a4-Cre; Ext1f/f and control mice." (PMID 36809261, 2023). "This elevation of S100A4 is also consistent with its overexpression in different types of metastatic cancer, and its established value as an indicator of poor prognosis and a therapeutic target for colon cancer." (PMID 32290283, 2020). "S100A4 was a small calcium-binding protein and played an oncogenic role in the development of multiple cancers, such as prostate cancer, breast cancer and colon cancer." (PMID 31866582, 2019). "The integrin subunit beta 6 protein mRNA (ITGB6) was induced in the two colon cancer cell lines by treatment with MACRO-CM from U937 macrophages, and the colon cancer metastasis-related protein S100A4 mRNA was induced in SW620 cells by treatment with THP-1 MACRO-CM." (PMID 29462209, 2018). "Thus, exploring the therapeutic potential of niclosamide in colon cancer patients in correlation to its target molecule S100A4 will enable us to evaluate this approach for broader uses in cancer therapy, where Wnt-signaling interference represents a rationale." (PMID 29544454, 2018). "Tissue samples of colon cancer from 148 patients who underwent colon resection due to colon cancer were analyzed by immunohistochemical staining to determine the protein expression levels of S100A4." (PMID 30111999, 2018). "Furthermore, Sack and colleagues performed high-throughput screening of 1,280 pharmacologically active compounds to identify a transcription inhibitor of S100a4 using a human colon cancer cell line." (PMID 29910813, 2018). "Nonsteroidal anti-inflammatory drug sulindac sulfide (sulindac) could inhibit colon cancer growth and metastasis by manipulation of the β-catenin signaling through reduction of S100A4 expression." (PMID 29069865, 2017).
colon carcinoma (continued). "Treatment of human colon cancer cells with interferon-gamma (IFN-γ) downregulates level of S100A4 mRNA in a time- and dose-dependent manner without associating with any cytotoxicities." (PMID 29069865, 2017). "Therefore, targeting the Wnt/β-catenin pathway with the subsequent inhibition of S100A4 gene expression will restrict formation of colon cancer metastases." (PMID 26880885, 2016). "Niclosamide inhibits S100A4 through the Wnt/β-catenin pathway in colon cancer." (PMID 27127879, 2016). "The most probable mechanism is methylation of the S100A4 promoter in normal cells, which efficiently prevents S100A4 expression, while the promoter is often hypomethylated in cancer cells, as has been observed in colon cancer cells." (PMID 25152734, 2014). "Nine of the 24 colon carcinoma specimens exhibited significant staining of the carcinoma cells, with three at a high level, and only in one of these specimens did the lymphocytes fail to stain for S100A4." (PMID 11875708, 2002). "However, higher mean levels of S100A4 mRNA in the RNA from the specimens of colon carcinomas (mean=30%±s.e." (PMID 11875708, 2002). "When in situ hybridization was carried out on some specimens of primary colon carcinoma which were positive for S100A4 mRNA in the quantitative RT–PCR assay, staining for this mRNA was evident in the carcinoma cells when the antisense probe, but not the sense probe was used." (PMID 11875708, 2002). "Thus, the levels of S100A4 have been determined in the primary tumour of colon carcinomas and corresponding liver metastases using quantitative polymerase chain reaction, in situ hybridization and immunocytochemical techniques." (PMID 11875708, 2002). "Additionally, by microarray analysis, several inflammatory cytokines, such as Infγ, Tnf, and Il1β were downregulated in the TME, including colon tumor cells, immune cells, fibroblasts, and other cells, in the S100a4-Cre; Ext1f/f mice compared to those in the control mice." (PMID 36809261, 2023). "Expression of the S100A4 protein in colon cancers may be an indicator of tumor progression and lymph node metastasis and may be useful for predicting the overall survival of the patients with colon cancer." (PMID 30111999, 2018). "However using in situ hybridization techniques, S100A4 mRNA is found associated with both the colon carcinoma cells as well as other non-parenchymal cell types including lymphocytes, which suggests that both these cell types are synthesizing S100A4." (PMID 11875708, 2002). "Several S100 proteins, including S100A1, S100A2, S100A4, and S100A11, were found in colon carcinomas with more aggressive disease and worse clinical outcomes." (PMID 41134679, 2025). "The layer of the Pan02 S.C. tumors in the S100a4-Cre; Ext1f/f mice was significantly thinner than that in the control mice, similar to MC38 S.C. colon tumors." (PMID 36809261, 2023). "It was shown that extracellular S100A4 promotes ERK and hypoxia signalling in a RAGE-dependent manner, mediating colon cancer cell motility." (PMID 32722137, 2020). "In subgroup analyses, S100A4 was of prognostic significance in TNM stages II and III and for patients with colon cancer and rectal cancer when analyzed separately." (PMID 27273130, 2016). "Furthermore, we asked if the prognostic value of S100A4 could be used to select colon cancer patients for adjuvant treatment, either to identify stage II patients who would benefit or to identify stage III patients with an excellent prognosis who might not profit from adjuvant chemotherapy." (PMID 27273130, 2016). "Interestingly, that stromal expression of SPARC and SPP1 was prognostic for the reduced RFS and PFS, respectively, only in rectal cancer patients, while S100A4 correlated with poor OS rates in CRC and colon cancer patients." (PMID 36895491, 2023).